Y_RNA (Y RNA )
Gene: Miscellaneous RNA gene on chromosome X (27,252,119 to 27,252,235, reverse strand). Ensembl gene ENSG00000252486.
Homologues: Orthologues: chimpanzee Y_RNA (99% identical), macaque Y_RNA (96% identical). Paralogues in human: Y_RNA (81% identical), Y_RNA (79% identical), RNY1 (79% identical), RNY1P11 (79% identical), Y_RNA (78% identical), RNY1P10 (77% identical), Y_RNA (77% identical), Y_RNA (76% identical), Y_RNA (75% identical), Y_RNA (74% identical), RNY1P8 (74% identical), RNY1P7 (73% identical), and 93 more.